TRAPPC14 (trafficking protein particle complex subunit 14)
Description:
Specific subunit of the TRAPP (transport protein particle) II complex, a highly conserved vesicle tethering complex that functions in late Golgi trafficking as a membrane tether. TRAPP II complex also has GEF activity toward RAB1A (By similarity). TRAPPC14 is dispensable for TRAPPII complex integrity but mediates RAB3IP preciliary vesicle trafficking to the mother centriole during ciliogenesis. Modulates YAP1 activity as transcriptional regulator.
Synonyms: C7orf43; MAP11; FLJ10925; MCPH25
Tractability: Antibody: its Gene Ontology location is reachable by antibodies, with high confidence.
Gene: Protein-coding gene on chromosome 7 (100,154,420 to 100,158,723, reverse strand). Ensembl gene ENSG00000146826.
Subcellular location: Cytoplasm, cytoskeleton, spindle; Vesicle; Midbody; Cytoplasm
Subcellular location (Human Protein Atlas): Vesicles; Centriolar satellite; Plasma membrane
Gene Ontology:
Molecular function: alpha-tubulin binding; protein binding
Biological process: cilium assembly; regulation of cell population proliferation
Cellular component: centriolar satellite; cytoplasm; midbody; mitotic spindle; TRAPPII protein complex; vesicle; spindle
Genetic constraint (gnomAD): Loss-of-function variants: 23 observed, 50.09 expected, observed/expected ratio (o/e) 0.46, 90% interval 0.33 to 0.65. The synonymous counts are far from expectation, so gnomAD's model fits this gene poorly and the ratio says little. Missense variants: 605 observed, 681.01 expected, observed/expected ratio (o/e) 0.89, 90% interval 0.83 to 0.95. Synonymous variants: 371 observed, 299.86 expected, observed/expected ratio (o/e) 1.24, 90% interval 1.14 to 1.35.
Homologues: Orthologues: chimpanzee TRAPPC14 (99% identical), macaque TRAPPC14 (99% identical), pig TRAPPC14 (98% identical), guinea pig TRAPPC14 (98% identical), rat Trappc14 (97% identical), dog TRAPPC14 (96% identical), mouse Trappc14 (96% identical), rabbit TRAPPC14 (93% identical), zebrafish trappc14 (65% identical), tropical clawed frog trappc14 (65% identical).
Diseases named in the same sentence as TRAPPC14 in open-access papers:
TRAPPC14 is named in the same sentence as 7 diseases in open-access papers, as found by Europe PMC text mining. Sharing a sentence is not in itself a finding about the gene and the disease. The quoted sentences say what the papers report.
microcephaly (3 papers, 2021 to 2022). A congenital or acquired developmental disorder in which the circumference of the head is smaller than normal for the person's age and sex. "Recently, TRAPPC14 mutations have been linked to MCPH25 in human and microcephaly phenotypes in the zebrafish model." (PMID 35111754, 2021).
TRAPPC14 also shares sentences with these, for which no sentence is quoted: acute lymphoblastic leukemia (1 paper); cancer (1); non-Hodgkin lymphoma (1); pancreatic ductal adenocarcinoma (1); Primary microcephaly (1); tumor (1).